U6 (U6 spliceosomal RNA )
Synonyms: LOC124906339
Gene: Small nuclear RNA gene on chromosome 3 (139,388,277 to 139,388,364, forward strand). Ensembl gene ENSG00000283418.
Gene Ontology:
Molecular function: U4 snRNA binding
Biological process: formation of quadruple SL/U4/U5/U6 snRNP; spliceosomal tri-snRNP complex assembly
Cellular component: U4/U6 x U5 tri-snRNP complex; U6 snRNP
Homologues: Orthologues: rat U6 (92% identical), guinea pig U6 (89% identical), pig U6 (86% identical), chimpanzee U6 (77% identical), chimpanzee U6 (73% identical). Paralogues in human: RNU6-1 (93% identical), RNU6-2 (93% identical), RNU6-3P (93% identical), RNU6-4P (93% identical), RNU6-5P (93% identical), RNU6-6P (93% identical), RNU6-9 (93% identical), RNU6-10P (92% identical), RNU6-12P (92% identical), RNU6-13P (92% identical), RNU6-17P (92% identical), RNU6-18P (92% identical), and 1284 more.